TMEM52 (transmembrane protein 52)
Tractability: Antibody: UniProt predicts a signal peptide or a membrane-spanning region; the Human Protein Atlas places it where antibodies can reach.
Gene: Protein-coding gene on chromosome 1 (1,917,589 to 1,919,329, reverse strand). Ensembl gene ENSG00000178821.
Subcellular location: Membrane
Subcellular location (Human Protein Atlas): Nucleoplasm; Plasma membrane
Gene Ontology:
Cellular component: membrane
Genetic constraint (gnomAD): Loss-of-function variants: 14 observed, 10.91 expected, observed/expected ratio (o/e) 1.28, 90% interval 0.84 to 1.85. The upper end of that interval is the gene's LOEUF score, 1.85, which puts it in group 6 of 6, group 1 being the genes least tolerant of losing a copy. Missense variants: 308 observed, 255.65 expected, observed/expected ratio (o/e) 1.2, 90% interval 1.1 to 1.32. Synonymous variants: 131 observed, 108.57 expected, observed/expected ratio (o/e) 1.21, 90% interval 1.05 to 1.39.
Homologues: Orthologues: chimpanzee TMEM52 (97% identical), macaque TMEM52 (80% identical), rabbit TMEM52 (68% identical), mouse Tmem52 (68% identical), rat Tmem52 (68% identical), guinea pig TMEM52 (63% identical), pig TMEM52 (63% identical), dog TMEM52 (53% identical), tropical clawed frog tmem52 (41% identical).
Diseases named in the same sentence as TMEM52 in open-access papers:
TMEM52 is named in the same sentence as 3 diseases in open-access papers, as found by Europe PMC text mining. Sharing a sentence is not in itself a finding about the gene and the disease. The quoted sentences say what the papers report.
tumor (2 papers, 2018 to 2020). "It clearly suggested that knockdown of TMEM52 inhibited tumor growth in mice." (PMID 30185771, 2018).
TMEM52 also shares sentences with these, for which no sentence is quoted: pancreatic cancer (2 papers); gastric adenocarcinoma (1).